HDAC11 (histone deacetylase 11)
Diseases named in the same sentence as HDAC11 in open-access papers (continued):
Sharing a sentence is not in itself a finding about the gene and the disease.
Obesity (11 papers, 2020 to 2025). Accumulation of substantial excess body fat. "Very recently, HDAC11 has been linked to the pathogenesis of obesity, diabetes, and diabetic complications." (PMID 36339432, 2022). "Higher levels of HDAC11 are associated with obesity, cancer stemness, and muscle regeneration." (PMID 40427555, 2025). "HDAC11 deficiency abrogates obesity and obesity-provoked metabolic syndrome, such as T2DM." (PMID 34071497, 2021). "In obesity, HDAC11 regulates the adipocyte phenotype through the demyristoylation of gravin-α and suppression of β-adrenergic receptor signaling." (PMID 40427555, 2025). "Previous studies on HDAC11 in the context of metabolism has predominantly concentrated on obesity and thermogenesis within adipose tissue, with scant investigation into the association between HDAC11 and MASLD." (PMID 39976110, 2025). "In DIO mice, HDAC11 absence was also shown to promote brown adipose tissue thermogenesis and white adipose tissue beigeing and ameliorate high-fat-induced obesity." (PMID 36875455, 2023). "A recent in vivo study in mice showed that selective inhibition of HDAC11 also promotes the development of brown adipose tissue and “browning” of white adipose tissue in obesity." (PMID 38125020, 2023). "In this review article, we summarize the role and possible mechanisms of HDAC11 in metabolic disorders, including obesity, metabolic inflammation, and diabetes and its complications, and provide detailed information about HDAC11 inhibitors developed so far." (PMID 36339432, 2022). "Recent studies have shown that HDAC11 is also critically involved in the pathogenesis of some metabolic diseases, including obesity, diabetes and complications of diabetes." (PMID 36339432, 2022). "HDAC11 knockout mice showed resistance to high-fat-diet-induced obesity and metabolic syndrome, suggesting that HDAC11 functions as a critical metabolic regulator." (PMID 32719718, 2020). "Unlike other classes of HDACs, the deacetylation activity of class IV HDAC is relatively weak, and as such, HDAC11 inhibitors might have a greater prospective in obesity treatment because of their relatively fewer side effects." (PMID 36875455, 2023). "Therefore, HDAC11 would be a prospective therapeutic target for obesity and the related metabolic effects." (PMID 36339432, 2022). "HDAC11 has been regarded to regulate metabolism and obesity." (PMID 34071497, 2021). "Interestingly, it was recently shown that loss of HDAC11 in mice promotes thermogenic capacity by increasing UCP1 expression, stimulates brown adipose tissue formation, attenuates obesity and metabolic syndrome in response to high fat diet, and increases fatty acid oxidation metabolism." (PMID 40220154, 2025). "HDACs are grouped into four principal classes, among which, HDAC11, the newly discovered HDAC enzyme, has been classified into Class IV HDAC and was regarded as a key factor in metabolism, obesity and immune functions." (PMID 40963862, 2025). "By binding to BRD2, HDAC11 inhibits the BAT transcriptional programme to suppress the thermogenic potential of adipose tissue, contributing to obesity." (PMID 36864020, 2023).
hepatocellular carcinoma (10 papers, 2020 to 2026). A malignant tumor that arises from hepatocytes. "In hepatocellular carcinoma, ST8SIA6-AS1 increased HDAC11 expression by targeting miR-4656, thus enhancing hepatocellular carcinoma cell proliferation and resistance to apoptosis." (PMID 33363573, 2020). "The role of HDAC11 in hepatocellular carcinoma (HCC) metastasis is complex and may depend on the specific cancer cell lines and preclinical models used." (PMID 39620228, 2024). "For example, the highly selective HDAC11 inhibitor B6 has demonstrated favorable pharmacokinetics in the treatment of metabolic dysfunction-associated fatty liver disease, and selective inhibition of HDAC6 by N-acylhydrazone can suppress hepatocellular carcinoma progression." (PMID 41444923, 2025). "Bi et al24 disclosed that deletion of HDAC11 increases LKB1 transcription by fostering histone acetylation in its promoter region, thus activating the AMPK signaling pathway and hindering the glycolysis pathway, which in turn suppresses cancer stemness and hepatocellular carcinoma progression." (PMID 37553792, 2023).
neuroblastoma (10 papers, 2016 to 2024). Neuroblastoma (NB) is the most common solid, extracranial childhood tumor. "Taken together, our experiments show that HDAC11 depletion in neuroblastoma cells causes formation of aberrant mitotic spindle assemblies followed by increased cell death." (PMID 28252645, 2017). "Taken together, the HDAC11 depletion phenotype characterized by cell accumulation in mitosis and aberrant spindle assembly formation is associated with downregulation of genes required for mitotic cell cycle progression in neuroblastoma cells." (PMID 28252645, 2017). "For example, inhibition of HDAC11 showed beneficial effects in neuroblastoma cells, suggesting that HDAC11 represents a promising target for the treatment of some cancer forms." (PMID 38279359, 2024). "HDAC11 plays important role in spindle assembly and the cell cycle during mitosis of neuroblastoma cells." (PMID 33742608, 2021). "HDAC11 depletion in MYCN-driven neuroblastoma cell lines strongly induces cell death, mostly mediated by apoptotic programs." (PMID 32719718, 2020). "Here we show that HDAC11 depletion in MYCN-amplified neuroblastoma cells triggers programmed cell death preceded by an accumulation of mitotic cells characterized by aberrant spindle assembly formation." (PMID 28252645, 2017). "We show here that HDAC11 depletion in MYCN-driven neuroblastoma cell lines strongly induces cell death, mostly mediated by apoptotic programs." (PMID 28252645, 2017). "Previous study indicated that HDAC11 blockage could induce apoptosis of tumor cells in neuroblastoma via preventing spindle assembly and cell cycle, but the exact role of HDAC11 in meiosis is largely unknown." (PMID 33742608, 2021). "HDAC11 depletion in neuroblastoma cell lines induces cell death mediated by apoptotic programs." (PMID 32719718, 2020). "Similarly, HDAC11 depletion in human neuroblastoma cells triggers caspase activation and caspase-dependent apoptosis." (PMID 32719718, 2020). "Here we deepen the understanding of HDAC11 function in neuroblastoma." (PMID 28252645, 2017). "The data indicate a significant role of HDAC11 for mitotic cell cycle progression and survival of MYCN-amplified neuroblastoma cells, and suggests that HDAC11 could be a valuable drug target." (PMID 28252645, 2017). "Other data demonstrated a significant role of HDAC11 in mitotic cell cycle progression and survival of MYCN-amplified neuroblastoma cells and suggested that HDAC11 is potentially a valuable drug target." (PMID 35359455, 2022). "Butyrate treatment has been shown to upregulate the expression of both HDAC11 (in bovine cell cultures and seabass liver) and HDAC6 (in mouse neuroblastoma and microglia cell cultures)." (PMID 32344633, 2020). "Our studies unravel a critical role for HDAC11 in cell cycle progression and viability of MYCN-amplified neuroblastoma cells." (PMID 28252645, 2017). "Taken together, our data illustrate an important role for HDAC11 in cell cycle progression and viability of MYCN-amplified neuroblastoma cells, and illuminates HDAC11 as a potential novel drug target for this subgroup of high-risk neuroblastomas." (PMID 28252645, 2017). "Transient HDAC11 knockdown in the SH-SY5Y and SK-N-AS neuroblastoma cell lines, which lack MYCN amplification, diminished ATP content by 21–38%." (PMID 28252645, 2017). "Our results in neuroblastoma cell lines with and without MYCN amplifications collectively highlight the significance of HDAC11 expression for cellular viability, particularly in the presence of MYCN amplification." (PMID 28252645, 2017).
liver cancer (7 papers, 2018 to 2026). An epithelial or non-epithelial malignant neoplasm that arises from the liver. "Together, these findings establish lysine myristoylation as a reversible regulatory modification on a spliceosomal component and reveal HDAC11-catalyzed de-myristoylation of SF3B2 as a mechanism that can tune alternative splicing in liver cancer cells." (PMID 42124652, 2026). "Lachenmayer and colleagues reported the significant upregulated expression of HDAC2, HDAC4, and HDAC11 in a cohort of liver cancer patients, whereas HDAC3 and HDAC5 were found to be associated with copy number gains in human HCC." (PMID 40940750, 2025). "Among them, HDAC7, HDAC4, SIRT7, KAT2A, and HDAC11 were the top five most upregulated genes, indicating that the expression of deacetylation-related genes played a dominant role in liver cancer compared with acetylation-related genes." (PMID 36124029, 2022). "Histone deacetylase 11 (HDAC11) is substantially expressed in liver cancer and is strongly tied to the prognosis of the disease." (PMID 35874626, 2022). "The effect of HDAC11 expression on the proliferation and migration of liver cancer was detected by the CCK-8 method and cell scratch test, respectively." (PMID 36124029, 2022). "The risk score calculated by the expression value of HDAC1, HDAC2, HDAC4, HDAC11, HAT1, and SIRT6 was an independent risk factor for liver cancer." (PMID 36124029, 2022). "Nevertheless, studies investigating the role of HDAC11 in liver cancer are limited." (PMID 40940750, 2025). "Overexpression of HDAC11 enhanced cell proliferation in liver cancer." (PMID 36124029, 2022). "The role of HDAC11 in liver cancer was identified by CCK-8 array and cell scratch test." (PMID 36124029, 2022).
renal fibrosis (6 papers, 2020 to 2025). A final common manifestation of a wide variety of chronic kidney diseases characterized by glomerulosclerosis and tubulointerstitial fibrosis. "To validate the functional role of HDAC11 in renal fibrosis, we further investigated the impact of loss of HDAC11 on renal fibrosis by using mice with global deletion of HDAC11 (HDAC11−/−or KO mice)." (PMID 40386380, 2025). "To investigate the role of HDAC11 in the development of renal fibrosis, we first examined the renal expression of HDAC11 in a murine model of renal fibrosis induced by UUO." (PMID 40386380, 2025). "Both pharmacological and genetic inhibition of HDAC11 attenuated the development of renal fibrosis and pEMT following UUO injury." (PMID 40386380, 2025). "In this study, we employed globally deleted HDAC11 mice and FT895, a highly selective inhibitor of HDAC11, to investigate the role and mechanism of HDAC11 in renal fibrosis." (PMID 40386380, 2025). "This study is the first to demonstrate the importance of HDAC11 in promoting the dedifferentiation of renal epithelial cells into a profibrotic phenotype and progression of renal fibrosis." (PMID 40386380, 2025). "This study is the first to demonstrate the critical role of HDAC11 in promoting the dedifferentiation of renal epithelial cells into a profibrotic phenotype and driving the progression of renal fibrosis." (PMID 41275091, 2025). "A recent study showed that inhibition of HDAC11 by quisinostat attenuated renal fibrosis induced by unilateral ureteral obstruction (UUO)." (PMID 41275091, 2025). "To elucidate the underlying mechanism by which HDAC11 induces EMT and renal fibrosis in the UUO model, we investigated the effect of HDAC11 inhibition on the phosphorylation of Smad3 (p-Smad3) and STAT3 (p-STAT3) in the kidney and cultured RTPCs." (PMID 40386380, 2025). "The application of Quisinostat, an HDAC11 inhibitor, has been demonstrated to effectively reverse renal fibrosis in this model." (PMID 38929505, 2024). "These novel insights into the functions of HDAC11 shed light on its potential as a therapeutic target for metabolic dysregulation in renal fibrosis." (PMID 38929505, 2024). "These insights into the multifaceted functions of HDAC11 shed light on its potential as a therapeutic target in the intricate landscape of renal fibrosis and metabolic dysregulation." (PMID 38929505, 2024). "Mechanistical studies demonstrate that HDAC11 contributes to renal fibrosis by suppressing expression of Kruppel-like factor 15, an anti-fibrogenic factor." (PMID 35559244, 2022). "Inhibition of HDAC11 attenuates renal fibrosis, blocks the pro-fibrogenic response induced by Ang II through interaction with activator protein 2 to activate KLF15 transcription." (PMID 36339432, 2022). "We report that expression levels of HDAC11 were up-regulated in the kidneys in several different animal models of renal fibrosis." (PMID 32363192, 2020). "Consistently, pharmaceutical inhibition with a small-molecule inhibitor of HDAC11 (quisinostat) attenuated unilateral ureteral obstruction (UUO) induced renal fibrosis in mice." (PMID 32363192, 2020). "We first made an attempt to establish a relationship between the expression levels of HDAC11 with renal fibrosis in both animal models and cell models." (PMID 32363192, 2020). "First, we relied exclusively on quisinostat to evaluate the effect of HDAC11 on renal fibrosis in vivo." (PMID 32363192, 2020). "Future studies employing tissue-specific HDAC11 knockout mice will hopefully provide solid genetic evidence to ascertain the role of HDAC11 in renal fibrosis." (PMID 32363192, 2020). "Inhibition of HDAC11 with a small-molecule compound quisinostat attenuates UUO-induced renal fibrosis in mice." (PMID 32363192, 2020). "Based on the observation that HDAC11 was up-regulated in the fibrotic kidneys, we sought to evaluate the effect of pharmaceutical inhibition of HDAC11 on renal fibrosis in the UUO model." (PMID 32363192, 2020).
renal fibrosis (continued). "Whereas previous studies have demonstrated a role for class I HDACs, class II HDACs, and class III HDACs in renal fibrosis, little attention has been paid to HDAC11 in this process." (PMID 32363192, 2020). "Here we report that the histone deacetylase HDAC11 promotes renal fibrosis by epigenetically repressing the transcription of KLF15, an anti-fibrogenic factor." (PMID 32363192, 2020). "It has been reported that other cell types, including fibroblasts, endothelial cells, and myeloid cells, can contribute to renal fibrosis; relatively little is known regarding the role of HDAC11 in these cells." (PMID 32363192, 2020). "Therefore, HDAC11 is essential for the activation of NF-κB signaling pathways during renal fibrosis and renal epithelial cell transformation." (PMID 40386380, 2025). "Moreover, HDAC11 expression are increased in the kidneys in animal models of renal fibrosis induced by unilateral ureteral obstruction and angiotensin II by suppressing Kruppel-like factor 15, an anti-fibrogenic factor." (PMID 36339432, 2022). "Since specific non-histone substrates for HDAC11 have yet to be identified, profiling the HDAC11 interactome in the kidneys may provide novel insight into its mode of action in the context of renal fibrosis." (PMID 32363192, 2020). "Therefore, our data provide the proof-of-concept for targeting HDAC11 as a potential therapeutic solution against renal fibrosis." (PMID 32363192, 2020). "In the present study we investigated the role of HDAC11 in renal fibrosis." (PMID 32363192, 2020). "Combined, these data suggest that there might be a positive correlation between HDAC11 and renal fibrosis both in vivo and in vitro." (PMID 32363192, 2020). "Finally, suppression of renoprotective molecules may constitute another mechanism by which HDAC11 promotes pEMT and renal fibrosis." (PMID 40386380, 2025). "Indeed, we found that the UUO-induced downregulation of these molecules was largely reversed by global deletion of HDAC11, indicating that HDAC11 may contribute to pEMT and renal fibrosis by suppressing the expression of multiple renoprotective factors." (PMID 41275091, 2025). "Our results demonstrate that either global deletion of HDAC11 or administration of FT895, attenuated renal fibrosis, pEMT and G2/M phase arrest in renal epithelial cells in a murine model of UUO." (PMID 40386380, 2025). "The global knockout of HDAC11 mice and FT895, a selective inhibitor of HDAC11, were utilized to assess the role of HDAC11 in renal fibrosis following unilateral ureteral obstruction (UUO) injury in mice." (PMID 40386380, 2025). "Therefore, targeting HDAC11 may be a promising therapeutic strategy to alleviate renal fibrosis." (PMID 40386380, 2025). "Moreover, HDAC11 may accelerate renal fibrosis by inducing renal inflammation." (PMID 40386380, 2025). "Therefore the issue as to whether HDAC11-driven synthesis of pro-fibrogenic molecules in tubular epithelial cells in response to Ang II treatment plays a significant role in the pathogenesis of renal fibrosis in vivo needs to be revisited in the future." (PMID 32363192, 2020). "Based on these insights, we speculate that HDAC11 may similarly act as a molecular switch in the STAT3 signaling cascade, linking HDAC11 activation to the development of EMT and renal fibrosis." (PMID 41275091, 2025). "Quisinostat is not a strictly specific HDAC11 inhibitor because it can, with equivalent potency, target several other HDACs that have been demonstrated to play regulatory roles in renal fibrosis." (PMID 32363192, 2020). "Thus, although our data implicate HDAC11 in NF-κB–mediated inflammatory and fibrogenic responses, additional studies will be required to determine whether HDAC11 acts independently or in cooperation with HDAC3 to regulate NF-κB signaling during renal fibrosis." (PMID 41275091, 2025).
renal fibrosis (continued). "However, quisinostat is not a specific HDAC11 inhibitor and can also target several other HDACs with equivalent potency—all of which have been shown to play regulatory roles in renal fibrosis, thus, it remains uncertain about the role and mechanisms of HDAC11 in renal fibrosis." (PMID 41275091, 2025). "Administration of quisinostat, a non-specific HDAC11 inhibitor, attenuated UUO-induced renal fibrosis and reduced Ang II-induced profibrotic response in cultured renal epithelial cells." (PMID 35559244, 2022).
Hodgkins lymphoma (5 papers, 2014 to 2025). A heterogeneous group of malignant lymphoid neoplasms of B-cell origin characterized histologically by the presence of Hodgkin and Reed-Sternberg (HRS) cells in the vast majority of cases. "An HDAC inhibitor study in human cell lines revealed that HDAC11 plays an essential role in regulating OX40 ligand expression in Hodgkin lymphoma." (PMID 32719718, 2020). "Additionally, inhibition of HDAC11 in Hodgkin lymphoma increases the expression of OX-40 ligand and inhibits the generation of IL-10 producing T regulatory cells in vitro." (PMID 25054063, 2014). "Small interfering RNAs (siRNAs) that selectively inhibited HDAC11 expression, significantly up-regulated OX40L, and induced apoptosis in Hodgkin lymphoma (HL) cell lines." (PMID 32719718, 2020). "HDAC11 negatively regulated the expression of interleukin-13/17 (IL-13/17) and tumor necrosis factor-alpha (TNF-α) in Hodgkin lymphoma, suggesting that HDAC11 inhibitors killed tumor cells by activating inflammatory responses, immune system activity, and apoptosis processes." (PMID 40421455, 2025). "Interestingly, HDAC11 was expressed in primary non-Hodgkin’s Lymphoma cases but not in Hodgkin’s Lymphoma cases." (PMID 25322459, 2014).